FOXP3 (forkhead box P3)
Diseases named in the same sentence as FOXP3 in open-access papers (continued):
Sharing a sentence is not in itself a finding about the gene and the disease.
tumor (continued). "Furthermore, a significant correlation was observed between the percentages of CD3 + PD-1+, CD3+ CD4+ PD-1+ or CD3+ CD4+ CD25+ FOXP3+ PD-1+ lymphocytes in PBMCs and the level of PD-L1 expression detected by IHC in tumor tissue (p < 0.05)." (PMID 30546030, 2018). "Recently, FOXP3 expression in different tumor cells has been found." (PMID 29549328, 2018). "Recent studies demonstrate that a subset of CD4+ T cells, referred to as CD4+CD25hi FoxP3+ naturally occurring Tregs, may accumulate in the tumor environment and suppress tumor-specific T-cell responses, thereby hindering tumor rejection." (PMID 30250191, 2018). "Additionally, tumor microenvironment, being also inflammatory, contains substantial amount of TGF-β cytokine associated with ability to convert CD4+CD25− into CD4+CD25+FoxP3+ cells." (PMID 29785404, 2018). "FOXP3 regulated the transcription level of miR‐198 by binding to its promoter sequence and overexpressed miR‐198 could suppress tumor cells’ proliferation and promote cell apoptosis." (PMID 30378283, 2018). "Considering that the depletion of tumor infiltrating FoxP3+ Tregs by anti-CD25 monotherapy resulted in only partial tumor control and large-dose possible complications, it was necessary to identify further interventions to increase clinical efficacy and tumor specific immune response." (PMID 30359281, 2018). "Immunofluorescence labelling for Foxp3 revealed an increase of Tregs in both tongue and squamous stomach of Krt76−/− mice compared to control mice, whether normal or tumour-bearing tissue." (PMID 30143634, 2018). "To further assess whether SENP3 is involved the regulation of Treg cell-mediated tumor immunosuppression by ROS, we carried out a side-by-side comparison using tumor-bearing Senp3+/+Foxp3-Cre, Senp3fl/flFoxp3-Cre, and Rag1−/− mice treated with NAC." (PMID 30089837, 2018). "In addition, a limited number of T cells (CD3+) was present in the tumor microenvironment, with a higher number of regulatory T cells (Foxp3+) and macrophages (CD11b+) as compared to activated cytotoxic T cells (CD8+/ Granzyme B+)." (PMID 30458852, 2018). "Next, FOXP3+ T cell high and low tumor infiltration were analyzed based on OS." (PMID 30003113, 2018). "In addition, we further performed the percentage of CD4+CD25+FoxP3+ by flow cytometry to understand the molecular mechanisms of regulatory T cells for tumor growth." (PMID 29416605, 2018). "Also, the expression of FoxP3 at the mRNA level in the tumor tissue was significantly reduced in the groups of medium and high doses of B-9-3." (PMID 30079021, 2018). "In addition, chemokine Cxcl1 and PD-L1 associated with immune tolerance were expressed in non-tumor tissue of the TME and correlated with the onset of macrophage and Treg infiltration as denoted by F4/80 and Foxp3 staining, respectively." (PMID 29487713, 2018). "The profile and the function of FOXP3+ T cells in tumour-draining ALNs is less well studied." (PMID 29390966, 2018). "Furthermore, a higher TGF-β concentration in tumor microenvironment was related to higher frequency of CD4+CD25+FoxP3+ cells, compared to peripheral blood of the same individual." (PMID 29785404, 2018). "Moreover, we identified FOXP3-driven and T follicular helper-like differentiation pathways in tumor microenvironments, and their bifurcation point, which is enriched with recently activated T cells." (PMID 30061879, 2018). "We further examined the FoxP3+ tumor infiltrating Tregs with IHC technology." (PMID 30359281, 2018). "For instance, Foxp3+ cell prevalence in tumor samples either alone or in ratio to CD8+ cell counts has gained attention as a potential tissue-based prognostic marker in multiple tumor types." (PMID 29320521, 2018). "While FOXP3 expression could barely be detected in tumor-free mice receiving DBY+CpG, 3–5% of Marilyn cells expressed FOXP3 in the TdLN of both tumor groups." (PMID 29844317, 2018).
tumor (continued). "Furthermore, by using a new CCA-based method, single-cell combinatorial CCA, we analyzed unannotated single-cell RNA-seq data from tumor-infiltrating T cells, and revealed that FOXP3 expression occurs predominantly in activated T cells." (PMID 30061879, 2018). "Thus, the percentage of Foxp3+ T cells in the tumor tissue seems to be related to sensitivity to intravesical BCG in the high-risk NMIBC." (PMID 30261082, 2018). "This links FOXP3 tumour suppressor activity in breast epithelia to the regulation of EMT." (PMID 29963231, 2018). "Indeed, FOXP3+ Treg cells were significantly increased within tumor and non-tumor normal tissues after BCG." (PMID 30344922, 2018). "Forkfead box P3 (FOXP3)+ Treg cells play the role of inhibiting anti-tumor immune response." (PMID 30619746, 2018). "Foxp3 is a marker of CD4+ immunosuppressive Treg cells, which could suppress an anti-cancer immune response and are associated with tumour progression." (PMID 30559928, 2018). "In addition, a limited number of T cells (CD3+) was present in the tumor microenvironment, with a higher number of regulatory T cells (Foxp3+) and macrophages (Cd11b+) as compared to a low infiltration of activated cytotoxic T cells (CD8+/ Granzyme B+)." (PMID 30458852, 2018). "The expression levels of both FOXP3 and miR‐198 were both lower in tumor tissues, and subsequent experiments proved that FOXP3 could lead to the rise of miR‐198 levels." (PMID 30378283, 2018). "Additionally, there was a significant increase in the CD8+ T cell population and reduction in CD4+ FOXP3+ Treg cells in the PSPEI-PAA nanocomplex treated mice tumor compared to PBS control mice tumor." (PMID 30960988, 2018). "Our experiment results also showed that hDKK1-hHSP70 vaccination could significantly decrease the percentage of CD4+CD25+Foxp3+ regulatory T cells in tumor-bearing mice." (PMID 29416605, 2018). "However, CTL-dependent anti-tumour responses are often suppressed by FOXP3+ Tregs that infiltrate tumours." (PMID 30142927, 2018). "Our results revealed that there were advantages to this treatment such as, partially depleting the number and function of FoxP3+ Tregs as well as enhancing the tumor-specific immune response, which could also synergize with anti-PD-1 therapy." (PMID 30359281, 2018). "Additionally, the level of CD3+CD4+FOXP3+ Treg cells in the tumor of PSPEI-PAA nanocomplex treatment group were declined compared to the PBS control group." (PMID 30960988, 2018). "For example, DC as the antigen-presenting cells (APC) is involved in the antitumor immune responses, while CD8+ T cell may dissolve and kill tumor cells, and CD4+ cell (including Foxp3+ Tregs) impose restrictions on tumor response." (PMID 29682534, 2018). "The cytotoxic T lymphocytes (CTLs, also CD8+ T cells, marked as CD3+CD8+ T cells) are pivotal immune cells directed against tumor cells susceptible to cell lysis, but CD4+Foxp3+ regulatory T cells (Treg) disturb antitumor immunity by suppressing the activities of effector T cells." (PMID 30619765, 2018). "FoxP3+ regulatory T cells (Tregs) may be partially responsible for an immune-suppressive tumor microenvironment, however, our results indicate that Tregs are also excluded from tumors to adjacent areas." (PMID 30283446, 2018). "Furthermore, in vivo, OA reduced tumor formation rate and attenuated Foxp3 expression in tumor-infiltrating lymphocytes." (PMID 28472762, 2017). "Likewise, DCs cause poor tumor immunogenicity if produced from indoleamine 2, 3-dioxygenase (IDO) and generate Foxp3-positive regulatory T cells after interface with other innate lymphocytes, for example, γδ-T cells and NKT cells." (PMID 29450136, 2017). "Indeed up to 22% of tumor infiltrating CD4 T lymphocytes express FOXP3, suggesting an important contribution of these cells in tumor escape." (PMID 29069740, 2017).
tumor (continued). "The multifactorial analysis included three variables of potential prognostic value, i.e. the N feature of the TNM Classification of Malignant Tumours (TNM) classification, infiltration intensity of M2 macrophages and CD8+/FoxP3+ (Treg) lymphocytes within the tumor stroma." (PMID 28343267, 2017). "To test whether TGFβ-signalling plays any role in FOXP3 induction in tumor-CD8+ Treg cells, we used specific pharmacological TGFβ receptor inhibitor (SB431542) or TGFβ neutralizing antibody." (PMID 28487507, 2017). "Therefore, patient survival rates are inversely correlated with the frequencies of FoxP3+ T cells in many tumor types." (PMID 29450136, 2017). "Furthermore, the increased percentages of Galectin-9+ tumour cells and Foxp3+ lymphocytes and the decreased percentage of CD8+ lymphocytes significantly differed between primary and recurrent NPC." (PMID 28871094, 2017). "Mφ and tumor in situ can secrete IL-10 to recruit Tregs to tumor site indicating that Mφ may affect the number of FOXP3+ Tregs by cytokines." (PMID 28029650, 2017). "Our group found that FOXP3 is also a breast epithelial cell-intrinsic tumor suppressor." (PMID 28637482, 2017). "Although the mechanism underlying the tumor suppression function of FOXP3 is not fully characterized, several genes and pathways have been found to be closely related." (PMID 28903735, 2017). "However, recent reports have indicated that the presence of CD4+ helper T lymphocytes, FoxP3+ Tregs and M2 cells can lead to favorable outcomes in certain tumor patients." (PMID 28977947, 2017). "In addition to their effects on cancer signaling, HDACi have distinct immune modulatory functions, including modulation of regulatory T cells (Treg), Foxp3 expression and changes in tumor-infiltrating lymphocytes (TILs) composition." (PMID 29371976, 2017). "The results of our study on CD8+/FoxP3+ lymphocytes indicate that the increase in the intensity of the infiltration of the tumor stroma by such defined subpopulation of Treg cells may be considered an unfavorable and independent prognostic factor." (PMID 28343267, 2017). "Notably, decreased ratios of tumor-infiltrating CD8+ T cells to FOXP3+ Tregs were shown to correlate with poor prognosis, especially in patients with breast, gastric, and ovarian cancer." (PMID 29375559, 2017). "It was observed that there was a significant increase in CD8+CD25+FOXP3+ T cell population with time indicating that we could successfully mimic the tumor microenvironment in in vitro condition." (PMID 28487507, 2017). "The same function of FoxP3+ T cells can be used to stimulate tumor growth." (PMID 29450136, 2017). "Here we show that Th17 cells are a source of tumour-induced Foxp3+ cells." (PMID 28290453, 2017). "An increased number of CD4+FOXP3+ Tregs correlates with poor prognosis in NSCLC suggesting that differentiation of CD4+ to CD4+FOXP3+ cells may contribute to tumor escape." (PMID 28402937, 2017). "In summary, the patients with high Galectin-9 expression in recurrent NPC was associated with a higher percentage of Tim-3+ lymphocytes and a more immunocompromised status (a lower percentage of CD8+ and higher percentage of Foxp3+ lymphocytes) in the tumour microenvironment." (PMID 28871094, 2017). "Therefore, we next sought to determine the cytokine profile of these FOXP3+CD8+ Treg cells generated in in vitro tumor model." (PMID 28487507, 2017). "To determine whether IL-21 is capable of preventing tumour-mediated FOXP3 induction in naïve T cells, we repeated our naïve T cell stimulations in the presence of 50% cancer cell supernatants, alone or with recombinant human IL-21." (PMID 28239749, 2017). "Moreover, FOXP3+ CD4+ Treg cells also influence effector T cell function in the microenvironment within tumor." (PMID 28545567, 2017).
tumor (continued). "Overall, we report the co-expression of different immunosuppressive molecules in FoxP3+Helios+ and FoxP3+Helios− Treg subsets, which might synergistically dampen T-cell activation and function and suppress tumor-specific immune responses in CRC patients." (PMID 28603527, 2017). "Therefore, we evaluated the paired immunologic expression of CD8+ lymphocytes, CD4+ lymphocytes, Foxp3+ lymphocytes, and the Galectin-9/Tim-3 pathway in the tumour microenvironment between primary and recurrent NPC from 95 patients." (PMID 28871094, 2017). "This information indicated a pivotal role of RUNX3 in FOXP3 regulation in tumor-CD8+ Treg cells." (PMID 28487507, 2017). "RT in combination with the anti‐PD‐L1 also significantly reduced infiltration of CD4+CD25+FOXP3+ T regulatory cells, further supporting the notion that PD‐L1 checkpoint inhibition together with RT can counteract the immunosuppressive tumor environment." (PMID 27932443, 2017). "However, the non-relapse group showed a positive intra-subtype TIL correlation between FoxP3+ cells at tumor margin and center, as well as a positive inter-subtype TIL correlation between FoxP3+ and Ki67+ cells." (PMID 28885584, 2017). "Since endogenous expression of FOXP3 in FOXP3+ tumor-infiltrating lymphocytes (TILs) is more than 100-fold higher than in breast epithelial cells, FOXP3+ TILs may contribute to the expression of FOXP3 in tumors." (PMID 28637482, 2017). "Furthermore, over-expression of FOXP3 obviously inhibited tumor proliferation and invasion, while FOXP3 down-regulation resulted in enhanced tumor growth and invasion." (PMID 28903735, 2017). "Interestingly, the patient 1 had an immune infiltration of tumor by lymphocytes CD3+, CD8+ and Treg FoxP3+ T cells, which is generally associated with a better response to anti PD-1 inhibitors especially for CD8." (PMID 28428880, 2017). "In addition, although it was known that FoxP3 was a specific marker for Tregs, some studies provided evidence that FoxP3 also expressed in tumor cells." (PMID 29209232, 2017). "Interestingly, MSCs in the tumor microenvironment can induce FOXP3 expression in TFH cells, thus mediating their conversion to TFR cells." (PMID 29340116, 2017). "Additionally, over-expression of Δ3,4-FOXP3 showed a significantly reduced inhibition on tumor growth (*P < 0.05, **P < 0.01) and migration (P = 0.018 and P = 0.039 for Hep3B and 97H, respectively) than full-length FOXP3." (PMID 28903735, 2017). "Human Foxp3 gene is located at Xp1 1.23, and it plays as a controller of the function of regulatory T-cells, which have a vital role in the process of forming microenvironment with immunosuppressive tumor." (PMID 28923073, 2017). "Expression of PD-L1 and numbers of CD8+ and Foxp3+ cells was examined in 17 paired tumor specimens." (PMID 28404915, 2017). "Thus, in addition to its documented ability to prevent de novo Treg generation, IL-21 is able to maintain this effect in the context of tumour-derived milieus that actively promote FOXP3 expression." (PMID 28239749, 2017). "In addition to TILs, expression of FOXP3 was also found in tumor cells and two independent reviewers evaluated it by percentage of positive tumor cells of total tumor cells." (PMID 28029650, 2017). "Specimens scored 1–4 were classified as ‘Tumor FOXP3-Low’ and 6–12 as ‘Tumor FOXP3-High’." (PMID 28716029, 2017). "In addition, TILs increase expression of PD-L1, tryptophan-catabolizing enzyme indoleamine-2,3-dioxygenase (IDO), and FoxP3+ Tregs in the melanoma tumor microenvironment." (PMID 27974689, 2017). "In contrast, knockdown of FOXP3 significantly increased the tumor formation and volume." (PMID 28591725, 2017). "By activation of direct and indirect mechanisms due to the inability to present antigen, TAMs predominantly represented in the tumor by the M2 phenotype induce the creation of lymphocytes showing the expression of the forkhead box P3 transcription factor (FoxP3+)." (PMID 28343267, 2017).
tumor (continued). "The level of Foxp3 expressing CD4+ Tregs is a critical component in suppressing tumor immunity." (PMID 28496193, 2017). "But how FOXP3 is induced and maintained in tumor-CD8+ Tregs is the Cinderella of the investigation." (PMID 28487507, 2017). "FOXP3 expression was most potently induced by tumours secreting higher levels of total and active TGFβ1 and this induction could be potently counteracted with IL-21, restoring T cell proliferation." (PMID 28239749, 2017). "Among these TILs, 2/3 of them were found in the perivascular niche; Foxp3+ T cells in these niches not only correlated with the tumor vessels but were also an independent predictor of shortened recurrence-free survival (RFS) (HR = 4.199, 95% CI 1.522–11.584, p = 0.006)." (PMID 29163521, 2017). "In contrast, IR exposure decreased the number of CD25+Foxp3+ Treg cells in the tumor sections." (PMID 28212561, 2017). "The tumor inhibitory effects of FOXP3 were rarely seen when COX2 was additionally knocked down." (PMID 28591725, 2017). "However, the biological function and clinical relevance of FOXP3 in tumor cells remain controversial." (PMID 28903735, 2017). "We therefore sought to determine whether E2 signalling through ERα is also capable of modulating FOXP3 expression and suppressive function of human tumour-infiltrating Treg cells in patients with CxCa." (PMID 29229929, 2017). "Th17 cells present a novel source of Foxp3+ Treg cells in the setting of tumour." (PMID 28290453, 2017). "Similarly, IL-21 was able to inhibit tumour-mediated FOXP3 induction in naïve CD4 T cells and restore their proliferative capacity." (PMID 28239749, 2017). "It has been reported that PD-1/PD-L1 interaction inhibits T lymphocyte proliferation, survival, and effector functions; promotes the differentiation of CD4+ T cells into Foxp3+ regulatory T (Treg) cells; and increases the resistance of tumor cells to cytotoxic T lymphocyte attacks." (PMID 28076847, 2017). "Altogether these results indicate that GATA3 might be playing a dual role in the regulation of FOXP3 transcription in tumor-CD8+ Treg cells." (PMID 28487507, 2017). "Recently, reports have demonstrated that FOXP3 is also expressed in tumor cells, suggesting that FOXP3 may have a broader role in cancer than initially thought." (PMID 28903735, 2017). "Recent studies showed that both recombinant GITR ligand (GITR-L) or agonist anti-GITR antibody (DTA-1) treatment of tumor-bearing mice led to a loss of tumor-infiltrating Tregs due to either cell depletion, reduced intra-tumor infiltration, or intra-tumor down-regulation of the Foxp3 expression." (PMID 28638937, 2017). "Although a high percentage of Galectin-9+ tumour cells and a high percentage of Foxp3+ lymphocytes in the tumour microenvironment were only marginally significant, a low percentage of CD8+ lymphocytes was a significant risk factor for relapse-free survival and overall survival." (PMID 28871094, 2017). "However, no combinatory effects on colonosphere, proportion of SP Cells, marker gene expression and tumor formation were observed when cells were treated with both FOXP3 transfection and COX2 inhibition." (PMID 28591725, 2017). "Quantitative real-time PCR experiments find that miR-31 has the most notable oncogenic targets AXIN1, which is involved in Wnt signaling pathway and forkhead family transcription factors FOXC2 and FOXP3, and this target gene and the two transcription factors are correlated with tumor stages." (PMID 29513198, 2017). "CD4+CD25+FOXP3+ Treg mediate immunosuppression and play an important role in tumour immune evasion." (PMID 28253320, 2017). "In vivo studies confirmed that FOXP3 promoted tumor growth and metastasis." (PMID 28716029, 2017). "Our results on the prognostic value of Foxp3+ TILs in this meta-analysis are consistent with this hypothesis and suggest that Foxp3+ TILs play pro-tumor roles." (PMID 28790445, 2017).